LILRA5 (leukocyte immunoglobulin like receptor A5)
Description:
May play a role in triggering innate immune responses. Does not seem to play a role for any class I MHC antigen recognition.
Synonyms: ILT-11; LIR-9; CD85f; ILT11; LILRB7; LIR9; CD85
Tractability: Antibody: UniProt places it where antibodies can reach, with high confidence; UniProt predicts a signal peptide or a membrane-spanning region; its Gene Ontology location is reachable by antibodies, with medium confidence.
Gene: Protein-coding gene on chromosome 19 (54,307,041 to 54,313,166, reverse strand). Ensembl gene ENSG00000187116.
Subcellular location: Cell membrane; Secreted (Isoform 3)
Pathways (Reactome):
Immune System: Immunoregulatory interactions between a Lymphoid and a non-Lymphoid cell
Gene Ontology:
Molecular function: inhibitory MHC class I receptor activity
Biological process: negative regulation of interleukin-12 production; negative regulation of interleukin-13 production; positive regulation of calcium ion transport; positive regulation of cell activation; positive regulation of inflammatory response; positive regulation of interleukin-1 beta production; positive regulation of interleukin-10 production; positive regulation of interleukin-6 production; positive regulation of MAPK cascade; positive regulation of protein tyrosine kinase activity; positive regulation of tumor necrosis factor production; cytokine-mediated signaling pathway; immune response-inhibiting cell surface receptor signaling pathway
Cellular component: cell surface; extracellular region; plasma membrane
Genetic constraint (gnomAD): Loss-of-function variants: 31 observed, 38.25 expected, observed/expected ratio (o/e) 0.81, 90% interval 0.61 to 1.09. The upper end of that interval is the gene's LOEUF score, 1.09, which puts it in group 4 of 6, group 1 being the genes least tolerant of losing a copy. Missense variants: 348 observed, 394.47 expected, observed/expected ratio (o/e) 0.88, 90% interval 0.81 to 0.96. Synonymous variants: 144 observed, 151.28 expected, observed/expected ratio (o/e) 0.95, 90% interval 0.83 to 1.09.
Homologues: Orthologues: chimpanzee LILRA5 (97% identical), macaque LILRA5 (88% identical), rat Lilrc2 (49% identical), rat Lilra5 (48% identical), mouse Lilra5 (47% identical), mouse Pira12 (47% identical), mouse Pira2 (46% identical), mouse Pira13 (45% identical), mouse Pira1 (45% identical), mouse Lilra6 (44% identical), rat LOC134485274 (44% identical), mouse Pirb (43% identical), and 3 more. Paralogues in human: LILRA6 (63% identical), LILRA4 (59% identical), LILRB3 (59% identical), LILRA1 (53% identical), LILRB5 (52% identical), LILRA2 (51% identical), LILRB1 (49% identical), LILRB2 (45% identical), LILRB4 (45% identical), NCR1 (35% identical), GP6 (35% identical), FCAR (33% identical), and 13 more.
Diseases named in the same sentence as LILRA5 in open-access papers:
LILRA5 is named in the same sentence as 21 diseases in open-access papers, as found by Europe PMC text mining. Sharing a sentence is not in itself a finding about the gene and the disease. The quoted sentences say what the papers report.
Sepsis (6 papers, 2023 to 2025). Sepsis is defined as life-threatening organ dysfunction caused by a dysregulated host response to infection. "To validate the expression of LILRA5 in sepsis, we established the CLP mouse model, and the blood of mice was derived." (PMID 40792106, 2025). "LILRA5 showed a higher expression in both mouse sepsis models and the THP-1 cell after lipopolysaccharide stimulation." (PMID 40792106, 2025). "In our manuscript, we validated LILRA5 expression using two independent bulk RNA sepsis cohorts showing consistent upregulation in human sepsis whole blood." (PMID 40792106, 2025). "Another study proved that LILRA5 was a diagnosed marker in both Escherichia coli- and S. aureus-induced sepsis." (PMID 40792106, 2025). "Our result validated the higher expression of LILRA5 in sepsis by two sepsis mouse models; moreover, after silencing LILRA5 expression in THP-1 cells, the OS activity was significant inhibited." (PMID 40792106, 2025). "In conclusion, our study has mapped the landscape of OS dynamics in sepsis and found that LILRA5+ macrophages in the early stage of sepsis exhibit the highest OS." (PMID 40792106, 2025). "In summary, our research has identified twelve genes, including CD3E, CD40LG, LILRA5, and FCER2, as potential diagnostic markers for sepsis." (PMID 40129981, 2025). "Future research should prioritize collaborative efforts to profile patient-derived macrophages at single-cell resolution, with a particular focus on LILRA5+ subsets in early sepsis." (PMID 40792106, 2025). "We identified 25 predictive genes, including LILRA5 and TNFAIP6, which had previously been associated with sepsis in other research." (PMID 38968271, 2024). "A previous study identified LILRA5 as a marker gene in sepsis." (PMID 40792106, 2025). "Our study showed that LILRA5+ macrophage may play a vital role in OS in sepsis; however, its biological mechanism needs to be further studied." (PMID 40792106, 2025). "A previous study showed that LILRA5 was a biomarker of sepsis." (PMID 40792106, 2025). "We found that the macrophage at the early stage had the most OS activity in sepsis and that LILRA5 may potentially be the gene regulating OS activity in this subtype of macrophage." (PMID 40792106, 2025). "Our team previously identified sepsis biomarkers (e.g., LILRA5 and monocyte differentiation signatures) via single-omics analysis, focusing on static phenotype association but lacking multi-omics integration, mechanistic validation, and therapeutic exploration." (PMID 41306770, 2025). "Targeting LILRA5 may offer therapeutic benefits by modulating ROS activity in macrophages during early sepsis." (PMID 40792106, 2025). "LILRA5 emerges as a promising gene for modulating macrophage-mediated OS in sepsis." (PMID 40792106, 2025). "Therefore, LILRA5 shows promise in regulating macrophage-mediated OS activity in sepsis." (PMID 40792106, 2025). "Real-time quantitative reverse transcription (qRT-PCR) and Western blotting validated expression of LILRA5 in both the cecal ligation and puncture (CLP) model and the lipopolysaccharide-induced sepsis model." (PMID 40792106, 2025). "Conversely, the expression of CCNB2, HJURP, KREMEN1, LILRA5, and SIPA1L2 was significantly higher in the sepsis group (P < 0.05)." (PMID 40129981, 2025). "In the training dataset, the expression of LILRA5, MGST1, PLBD1, and S100A9 was upregulated significantly in the sepsis group compared to the normal group." (PMID 40792106, 2025). "LILRA5, MGST1, PLBD1, and S100A9 were selected as hub genes and significantly upregulated in sepsis." (PMID 40792106, 2025). "Moreover, in the test datasets, the expression of LILRA5, MGST1, PLBD1, and S100A9 was significantly elevated in the sepsis group." (PMID 40792106, 2025). "Our single-cell sequencing data demonstrated that sepsis marker genes were highly elevated in CD16+ monocytes, including NAP1L1, CFD, BID, BCL2A1, MALAT1, RNH1, and LILRA5 genes." (PMID 39294473, 2024).
Sepsis (continued). "Notably, the key genes upregulated during sepsis are responsible for regulating cell cycle progression and differentiation (i.e., S100A8 and S100A9) and immune responses (i.e., ANXA1, APOBEC3A, LILRA5, CR1, and CD55)." (PMID 37298316, 2023).
Obesity (3 papers, 2019 to 2026). Accumulation of substantial excess body fat. "Limited literature concerning LILRA5 changes associated with liver steatosis, MetS, or obesity, both at gene expression level or plasm abundance, has been reported." (PMID 39017916, 2025). "LILRA5 stimulates innate immune responses via cytokine signaling, reflecting inflammatory mechanisms that can suppress HDL in obesity." (PMID 41512839, 2026).
rheumatoid arthritis (3 papers, 2016 to 2021). A chronic, systemic autoimmune disorder characterized by inflammation in the synovial membranes and articular surfaces. "LILRA5 is involved in both macrophage activation and secretion of several proinflammatory cytokines, and LILRA5 has a potential impact on pathogenesis of rheumatoid arthritis." (PMID 31093495, 2019). "LILRA5 expression has been described for macrophages and induces production of proinflammatory cytokines and IL-10 in a rheumatoid arthritis model." (PMID 27654936, 2016). "Rheumatoid arthritis patients abundantly express LILRA2, LILRA3, LILRA5, and LILRB2, with the presence of LILRA2, LILRA5, and LILRB2 significantly correlating with disease activity." (PMID 34737739, 2021).
viral infection (2 papers, 2022 to 2023). "Purified mouse LILRB4 (mLILRB4) proteins, as well as human LILRB4 (hLILRB4) proteins, bind to ZIKV directly in a dose-dependent manner, whereas LILRA5 does not, suggesting that LILRB4 could directly modulate viral infection of cells." (PMID 35132958, 2022).
acute myeloid leukemia (1 paper, 2016). Acute myeloid leukemia (AML) is a group of neoplasms arising from precursor cells committed to the myeloid cell-line differentiation. "High let-7a-2-3p expression was associated with reduced expression of oncogene JDP2 and leukocyte immunoglobulin-like receptor (LILRA5/6, LILRB2/3), which are correlated with poor prognosis in cytogenetically normal acute myeloid leukemia (CN-AML) patients." (PMID 27179712, 2016).
amyotrophic lateral sclerosis (1 paper, 2025). Amyotrophic lateral sclerosis (ALS) is a neurodegenerative disease characterized by progressive muscular paralysis reflecting degeneration of motor neurons in the primary motor cortex, corticospinal tracts, brainstem and spinal cord. "Our bioinformatics analysis revealed that the interaction network composed of LILRA5, HNRNPL and AGBL3 was significantly enriched in functions such as’ RNA splicing regulation ‘and’ metal peptidase activity ‘, and was closely related to the ‘amyotrophic lateral sclerosis pathway (hsa05014)’." (PMID 41379792, 2025).
clear cell renal cell carcinoma (1 paper, 2025). "LILRA1, LILRA2, LILRA5, LILRB1, LILRB2, and LILRB3 are differentially expressed across several cancer types, including lung squamous cell carcinoma, lung adenocarcinoma, papillary renal cell carcinoma, and clear cell renal cell carcinoma, suggesting a potential pan-cancer role for LILR family genes." (PMID 40843931, 2025).
depression (1 paper, 2025). "The drug-gene interaction analysis focused on LILRA5, CYP4F2, and KISS1R, which are implicated in the comorbidity of depression and renal failure." (PMID 40595897, 2025). "PPI network analysis identified 23 hub genes, including CYP4F2, KCNA3, KISS1R, LILRA5, and ZC3H12D, as key players in the shared pathophysiology of ESRD and depression." (PMID 40595897, 2025). "Further, protein-protein interaction (PPI) network analysis pinpointed five central genes CYP4F2, KCNA3, KISS1R, LILRA5, and ZC3H12D as pivotal players in the shared pathophysiology of depression and renal failure." (PMID 40595897, 2025). "We discovered that the five key genes CYP4F2, KCNA3, KISS1R, LILRA5 and ZC3H12D remained different after Venn diagram overlap of DEGs across depression and renal failure datasets." (PMID 40595897, 2025). "PPI network analysis identified CYP4F2, KCNA3, KISS1R, LILRA5, and ZC3H12D as key players in the shared pathophysiology of ESRD and depression." (PMID 40595897, 2025). "Notably, LILRA5, CYP4F2, and KISS1R consistently exhibited higher expression levels in the disease groups compared to controls, suggesting their prominent roles in the pathophysiology of depression and chronic nephritis." (PMID 40595897, 2025).
E. coli infection (1 paper, 2019). "As for the eight common genes screened out in all four datasets, CEACAM1, GK, PFKFB3, and TNFAIP6 emerged repeatedly in the S. aureus group, but CEACAM1, IL18RAP, LILRA5, PFKFB3, PSTPIP2, and SOCS3 emerged in the E. coli infection." (PMID 31093495, 2019).
osteoporosis (1 paper, 2025). A condition of reduced bone mass, with decreased cortical thickness and a decrease in the number and size of the trabeculae of cancellous bone (but normal chemical composition), resulting in increased fracture incidence. "After identifying LILRA5, HNRNPL, and AGBL3 as common hub genes for Osteoporosis and stroke, their synergistic regulatory mechanisms further confirm the molecular basis of comorbidity." (PMID 41379792, 2025). "Bioinformatics analysis identified LILRA5, HNRNPL and AGBL3 as common key genes for Osteoporosis and stroke, and these genes were highly effective in diagnosing both diseases." (PMID 41379792, 2025).
steatosis (1 paper, 2025). Increased lipid within the cytoplasm of cells. "The study identified five circulating proteins associated with the steatosis grade in the liver: Cathepsin O (CTSO), Cadherin 2 (CDH2), Leukocyte immunoglobulin-like receptor subfamily A member 5 (LILRA5), and Serpin B6 (SERPINB6); and Prolyl endopeptidase (FAP)." (PMID 39017916, 2025). "CDH2, CTSO, Leukocyte Immunoglobulin Like Receptor A5 (LILRA5), BMI, waist circumference, HOMA-IR, and FLI, among others, significantly correlated with the steatosis degree." (PMID 39017916, 2025). "The candidates to be combined in future algorithms for steatosis are CTSO, CDH2, LILRA5, SERPINB6, and FAP." (PMID 39017916, 2025).
bacterial infection (1 paper, 2025). "In this article, we shortlisted activated target genes in monocytes during acute bacterial infection, including VNN1, NLRC4, CYP1B1, PFKFB3, LILRA5, NFKBIA or NFKBIZ." (PMID 40581066, 2025). "Other monocyte informative genes were also activated in patients with bacterial infection including NLRC4, CYP1B1, PFKFB3, LILRA5, NFKBIA, and NFKBIZ." (PMID 40581066, 2025).
LILRA5 also shares sentences with these, for which no sentence is quoted: COVID-19 (2 papers); cancer (1); dementia (1); liver steatosis (1); lung adenocarcinoma (1); lung squamous cell carcinoma (1); papillary renal cell carcinoma (1); renal failure (1); Stroke (1).